GNAS (GNAS complex locus)
Diseases named in the same sentence as GNAS in open-access papers (continued):
Sharing a sentence is not in itself a finding about the gene and the disease.
medulloblastoma (10 papers, 2010 to 2025). A malignant, invasive embryonal neoplasm arising from the cerebellum. "On the contrary, GNAS has been identified as a potent tumor suppressor in sonic Hedgehog-driven medulloblastoma which displays a substantial loss of GNAS-containing chromosomal region." (PMID 39117798, 2024). "Mutations in GNAS has been discovered in human medulloblastoma and it has been demonstrated in mice that GNAS loss leads to YAP activation and tumorigenesis." (PMID 31072060, 2019). "GNAS activity was shown to suppress SHH signaling and loss of GNAS in neural stem/progenitor cells induces medulloblastoma formation with full penetrance." (PMID 30279357, 2018). "Notably, loss or reduced expression of GNAS has been associated with increased tumor aggressiveness and poor survival in medulloblastoma." (PMID 40534859, 2025). "A recent study showed that medulloblastomas can be subdivided into two prognostically different subgroups according to the G-protein alpha subunit Gsα (GNAS) levels: SHH-mutated GNAS-high tumors have a markedly better overall survival compared to SHH-mutated, GNAS-low tumors." (PMID 30279357, 2018). "Rolipram and another PDE4 inhibitor, eggmanone, suppress SHH and Hedgehog signaling thereby inhibiting medulloblastoma growth in GNAS-mutant mice." (PMID 38233872, 2024). "According to these observations it was concluded that GNAS is a tumor suppressor gene for medulloblastoma formation." (PMID 30279357, 2018). "Previous in vivo studies have shown that the GNAS gene can act as a tumor suppressor in Hh-driven medulloblastomas." (PMID 28789624, 2017). "While mutant GNAS drives pancreatic tumorigenesis by promoting PKA-mediated suppression of SIK, GNAS acts as a tumor suppressor in neuroblastoma, medulloblastoma and basal cell carcinoma of skin." (PMID 38233872, 2024). "As expected, overexpression of SHH itself significantly increased proliferation, and overexpression of GNAS, which has been identified as a tumor suppressor gene in the SHH subtype of medulloblastoma, significantly inhibited proliferation." (PMID 36995257, 2023).
pancreatic adenocarcinoma (10 papers, 2019 to 2025). "Our analysis showed that pancreatic adenocarcinoma specimens with wild-type KRAS status were 3.5 times more likely to have a GNAS mutation." (PMID 40002298, 2025). "Moreover, GNAS mutation can be used to distinguish carcinomas derived from IPMNs and concomitant pancreatic adenocarcinoma." (PMID 34884643, 2021). "Through TCGA, the most common mutations in GNAS are found in endometrial carcinomas (7.3%), colorectal malignancies (4.7%), adrenocortical carcinomas (5.5%), stomach adenocarcinomas (5.7%), esophageal carcinomas (4.9%), pancreatic adenocarcinomas (5.6%), and ulcerative carcinomas (5.7%)." (PMID 40969301, 2025). "KRAS mutations are found in over 90% of conventional pancreatic adenocarcinomas, indicating that the KRAS pathway is heavily associated with invasion, whereas GNAS mutations are less commonly identified." (PMID 40002298, 2025).
colloid carcinoma (9 papers, 2015 to 2025). "Studies had shown colloid carcinomas of the pancreas were arose in association with IPMN, and GNAS codon 201 mutations can be identified in the majority of colloid carcinoma, which are also verified in present study." (PMID 35180847, 2022). "Liu and colleagues reported KRAS and GNAS are the most commonly mutated genes in LAMNs and low-grade mucinous adenocarcinomas with PMP." (PMID 33712927, 2021). "These are well identified by the IPMN-derived morphological category and by the association with GNAS mutations and include all cases of colloid carcinomas." (PMID 34201897, 2021). "Consistent with this dichotomy, molecular data confirm a distinct mutational profile of intestinal type and related colloid carcinomas, characterized mainly by the higher prevalence of GNAS mutations and lower rate of KRAS alterations." (PMID 34201897, 2021). "GNAS only mutated tumors are almost all of the intestinal subtype and GNAS mutated colloid carcinomas harbor way less KRAS mutations than GNAS mutated tubular lesions (40–50% versus 80%)." (PMID 34201897, 2021). "GNAS mutations were found in all three colloid carcinomas and six conventional PDACs." (PMID 35180847, 2022). "Colloid adenocarcinomas arising from IPMNs were associated with a high frequency of GNAS mutation." (PMID 27512631, 2016). "GNAS mutations were present in all four colloid carcinomas and two conventional PDAs." (PMID 25855536, 2015). "Noteworthy, the studies reporting 50% or more GNAS mutated IPMC were also those that included notably high proportions of intestinal type and/or colloid carcinomas." (PMID 34201897, 2021). "Tissue GNAS mutations are associated with IPMN (58–79%; OR 30, 95% CI 7.143–127.622), IPMN-associated adenocarcinoma (36%) and mucinous carcinoma (78%)." (PMID 30196428, 2018). "Among these, no colloid carcinomas were observed, but GNAS mutated PDACs showed better differentiation than controls." (PMID 34201897, 2021). "Notably, mucinous adenocarcinoma with intrapulmonary metastasis harboring concurrent KRAS and GNAS mutations was identified in a 14-year-old boy with type 1 CPAM, suggesting that GNAS mutations may play a critical role in tumor progression and metastasis." (PMID 40296044, 2025). "Similarly, Liao and colleagues recently showed that HAMN and LAMN share high rates of KRAS and GNAS co-mutations supporting a common histogenesis and distinguishing them from mucinous adenocarcinoma, which is characterized by KRAS mutations in the absence of GNAS alterations." (PMID 33712927, 2021).
osteosarcoma (9 papers, 2014 to 2025). A usually aggressive malignant bone-forming mesenchymal neoplasm, predominantly affecting adolescents and young adults. "GNAS mutations, depending on the molecular detection method used, can be identified in 45%–88% of FD cases and are not present in other fibro-osseous lesions such as cemento-ossifying fibroma, cemento-osseous dysplasia or low-grade osteosarcoma." (PMID 31838586, 2020). "Analysis of fibro-osseous lesions resembling FD have suggested that FD-related GNAS activating variants can also be found in a subset of osteosarcomas providing a genetic link that may explain the numerous prior case reports of increased osteosarcoma risk in patients with FD." (PMID 40781626, 2025).
pituitary tumor (9 papers, 2018 to 2025). A benign or malignant neoplasm affecting the pituitary gland. "The evidence support the idea that driver gene mutations such USP8 and GNAS can be used to develop a pituitary tumor in vitro model." (PMID 35954322, 2022). "Recently, a comprehensive genome-wide analysis of functional pituitary tumors also reported that only GNAS mutations were recurrent in GHomas, consistent with previous reports." (PMID 35954322, 2022). "Activating mutations in GNAS were demonstrated to induce endocrine cell hyperplasia, with activating mutations found in 28% of growth hormone-secreting pituitary tumors and 5% of thyroid adenomas." (PMID 34943797, 2021). "Compensatory mutations with opposite functional outcomes have been reported in pituitary tumors, where the effect of activating GNAS mutations can be replaced by inactivating mutations on Gi/o proteins or on AIP." (PMID 31337866, 2019). "This profile is similar to that of sporadic PITs but differs from that of other hereditary pituitary tumors (due to GNAS, AIP, or PRKAR1A defects) that secrete primarily GH." (PMID 31263451, 2019). "Epigenetic modifications have become increasingly important in understanding tumorigenesis, as most pituitary tumors are sporadic with no known genetic driver mutations (with the exception of a significant proportion of GH-PTs and ACTH-PTs with GNAS and USP8 mutations, respectively)." (PMID 32201880, 2020).
colon cancer (8 papers, 2014 to 2025). "APC, SMAD4, NF1 (neurofibromin 1), ARID5B, NCOR1 (nuclear receptor corepressor 1), IGFR1R (insulin like growth factor 1 receptor) and GNAS (GNAS complex locus) were the most often mutated genes in patient-derived colon cancer cells." (PMID 33050525, 2020). "Taken together, these data indicate that GNAS mutant colon tumors commonly have synchronous mutations in KRAS or BRAF, are right-sided in location, and are associated with a villous morphology." (PMID 24498230, 2014). "In this study we find that GNAS mutations associate with a distinct subclass of colon cancers that is typified by location in the proximal colon, by having coincident KRAS or BRAF mutation, and by association with villous morphology." (PMID 24498230, 2014). "Here we show that GNAS mutant colon tumors harbor recurrent KRAS or BRAF mutations, target the anatomic proximal “right-sided” colon, and exhibit a villous morphology." (PMID 24498230, 2014). "Of the 428 colon tumors assayed, mutations in GNAS were present in 10 of the samples (2.3%), indicating this is a significant, albeit infrequent, mutation in colorectal tumors." (PMID 24498230, 2014). "Oncogenic mutations in GNAS have been described in a number of neoplasms including those of the pituitary, kidney, pancreas, and, more recently, in colon cancer." (PMID 24498230, 2014). "APC, SMAD4 (SMAD family member 4), NF1 (neurofibromin 1), ARID5B, NCOR1 (nuclear receptor co-repressor 1), IGFR1R (insulin like growth factor 1 receptor) and GNAS (GNAS complex locus) were the most often mutated genes in patient-derived colon cancer cells, YUMC-C1 and YUMC-C2." (PMID 33050525, 2020). "Among GNAS mutant colon cancers, we identified mutations in the KRAS and BRAF oncogenes in nine of the ten (90%) cases, a fraction that is significantly higher than the overall frequency of KRAS and BRAF mutations in the tumor cohort (P<0.0305, Fisher's exact test)." (PMID 24498230, 2014). "Although the frequency of GNAS mutant colon cancers is 2.3%, we find these tumors constitute a distinct molecular-pathologic subclass of colon cancer." (PMID 24498230, 2014).
gastric cancer (8 papers, 2014 to 2025). A primary or metastatic malignant neoplasm involving the stomach. "Using different filtering approaches, we identified a multitude of novel potentially damaging mutations and could show a validated association between a mutation in GNAS and gastric cancer." (PMID 28683819, 2017). "The discovery of methylated region was found in the first exon region of GNAS which is hypomethylated in LNM + EGC in our study, suggesting that imprinted domains in GNAS could play a role in gastric cancer metastatic development as well." (PMID 35115040, 2022). "Statistical analysis showed that the TE, BAE, and MAE scores of imprinted genes GNAS, GRB10, and SNRPN were significantly increased in malignant samples for almost all ten cancer types (p < 0.01), with the only exception of SNRPN in gastric cancer." (PMID 32448196, 2020).
hepatocellular carcinoma (8 papers, 2017 to 2025). A malignant tumor that arises from hepatocytes. "In addition, GNAS mutations are also involved in hepatocellular carcinoma, kidney cancer, and colorectal tumors." (PMID 29104223, 2017). "This included, most notably, guanine nucleotide-binding protein G(s) subunit alpha isoforms (GNAS), which mediates LPS-mediated signaling in hepatocellular carcinoma models." (PMID 36581203, 2023). "This study was based on hepatocellular carcinoma (HCC) patients of early-stage to explore the diagnostic capability and possible production causes of anti-GNAS autoantibody." (PMID 38107305, 2023). "The aim of this study was to explore the value of autoantibody to GNAS in the early detection of hepatocellular carcinoma (HCC)." (PMID 35052777, 2022). "Additionally, we examined GNAS protein expression level in several hepatoma cell lines." (PMID 32123532, 2020). "Our study explores the regulatory role of GNAS during STAT3 phosphorylation in HCC cells and demonstrates that GNAS promotes STAT3 Y705 phosphorylation by inhibiting TPTEP1 binding to STAT3, which mediates inflammation-induced hepatocellular carcinoma cell lines’ proliferation and invasion." (PMID 32123532, 2020).
ovarian carcinoma (8 papers, 2012 to 2025). A malignant neoplasm originating from the surface ovarian epithelium. "Mutations in GNAS have been documented in mucinous, clear cell, and serous advanced ovarian cancers; thus, our findings in the endometrioid ovarian cancer subtype should be considered as a very infrequent somatic mutational event." (PMID 31197119, 2019). "On the whole, our study identified five key SRGs, including the risk genes AUP1, PI3 and CCDC80, as well as the protective genes CD200 and GNAS and elucidated their prognostic potential in ovarian cancer." (PMID 40534859, 2025). "Through single-cell analysis, we further identified five potential prognostic biomarkers associated with the ovarian cancer cell functional pathway and TIME: three risk genes PI3, AUP1 and CCDC80 and two protective genes CD200 and GNAS." (PMID 40534859, 2025). "Through integrated machine learning and single-cell analysis, we identified five prognostic-associated SRGs (PI3, AUP1, CD200, GNAS and CCDC80) regulated by global SUMOylation levels in ovarian cancer." (PMID 40534859, 2025). "In the present study, both univariate Cox regression analysis and integrated machine learning approaches identified CD200 and GNAS as protective biomarkers in ovarian cancer." (PMID 40534859, 2025). "The amplification of GNAS has been shown to be connected with resistance to cetuximab in patients with metastatic colorectal cancer (RAS w/t tumor) and also to be associated with poor progression-free survival in patients with ovarian cancer." (PMID 35141142, 2021). "However, the mechanisms through which CD200 and GNAS influence ovarian cancer prognosis remain unclear and require further investigation through in vitro and in vivo experiments." (PMID 40534859, 2025). "Analysis of transcriptomic data from the TCGA HGSOC dataset suggests that SRC and GNAS expression may be associated with increased expression of EMT and cancer cell stemness markers, supporting the notion that these molecules may be able to drive EMT in ovarian cancers." (PMID 38097740, 2024).
adrenal adenomas (7 papers, 2016 to 2024). "Somatic activating mutations of GNAS, which encodes the α-subunit of the stimulatory G protein (GSα), occur in 5% to 17% of adrenal adenomas which are cortisol secreting." (PMID 32266384, 2020). "In adrenal gland adenomas GNAS SWI arginine and p.L207R mutations in the cAMP activated enzyme PRKACA are mutually exclusive." (PMID 31337866, 2019). "This patient harbored a GNAS activating mutation, and presented with a mild cortisol- and androgen-producing adrenal adenoma." (PMID 30670014, 2019). "Adrenal adenomas harboring mutations in PRKACA or GNAS are generally smaller and present with more overt hypercortisolism than the non-mutant types." (PMID 27606678, 2016).
ossifying fibroma (7 papers, 2012 to 2025). A bone benign neoplasm that is located_in the mouth and results_in an overgrowth of gingival tissue due to irritation or trauma. "We were able to identify a single reference, presented as an abstract, of GNAS mutation in two examples of florid cemento-osseous dysplasia and one case of cemento-ossifying fibroma." (PMID 23230423, 2012).
adrenal tumors (6 papers, 2003 to 2022). "Overall, immunohistochemical analysis revealed higher expression of StAR in adrenal tumors with mutations in PRKACA, GNAS, and PRKAR1A than in wild-type tumors, which exhibited lower expression of StAR." (PMID 27606678, 2016). "Somatic mutations that constitutively activate WNT/β-catenin (CTNNB1), G-protein (GNAS, GNAQ, GNA11), and cAMP/protein kinase A (PKA) (GNAS, PRKACA) signaling can drive unrestrained cell proliferation and survival in diverse tumors, including adrenal tumors." (PMID 36004349, 2022).
breast neoplasm (6 papers, 2022 to 2025). A benign or malignant neoplasm of the breast parenchyma. "High GNAS expression in a breast tumour tissue showed a close correlation with the reduced overall survival, frequent distal metastasis, advanced clinical stage, stronger cell proliferation and enhanced cancer cell migration." (PMID 35975235, 2022). "ZNF703, CTCF, and GNAS alterations were exclusively observed among HR‐positive/HER2‐negative patients, which was consistent with what was observed in a study on 11 616 breast tumors." (PMID 35971249, 2022).
glioma (6 papers, 2010 to 2025). A benign or malignant brain and spinal cord tumor that arises from glial cells (astrocytes, oligodendrocytes, ependymal cells). "In addition, the IDH1.R132H, GNAS.R201C, and EGFR.T790M mutations in Glioma, EGC, and NSCLC were the most significantly different point mutations (p = 0.00021, 0.00027 and 0.0011, respectively)." (PMID 29038591, 2017).
hyperphosphatemia (6 papers, 2011 to 2024). Abnormally high level of phosphate in the blood. "The second pathway is the impairment of brain Pi homeostasis, either by hyperphosphatemia or by disrupted transport of phosphate in the brain; these patients suffering from this pathway defects may have mutations in SLC20A2, XPR1, or GNAS gene and usually show significantly increased CSF Pi levels." (PMID 36443312, 2022).
myxofibrosarcoma (6 papers, 2012 to 2024). A malignant fibroblastic neoplasm arising from the soft tissue. "Since GNAS pathogenic variants are absent in low-grade myxofibrosarcoma, detection of these pathogenic variants can be a useful differential diagnosis." (PMID 38317844, 2024).
polyostotic fibrous dysplasia (6 papers, 2015 to 2024). Fibrous dysplasia affecting more than one bone. "The skeletal phenotype unique to the proband was due to an additional pathogenic somatic mutation in GNAS (NM_000516.7:c.601C>T; p.(Arg201Cys)), which leads to polyostotic fibrous dysplasia." (PMID 38528055, 2024). "Gs-α is encoded by GNAS and activating mutations of GNAS gene result in constitutively active GPCR and clinically McCune-Albright syndrome, polyostotic fibrous dysplasia, and various endocrine tumors." (PMID 26148701, 2015).